ARSK (arylsulfatase family member K)
Description:
Catalyzes the hydrolysis of pseudosubstrates such as p-nitrocatechol sulfate and p-nitrophenyl sulfate. Catalyzes the hydrolysis of the 2-sulfate groups of the 2-O-sulfo-D-glucuronate residues of chondroitin sulfate, heparin and heparitin sulfate. Acts selectively on 2-sulfoglucuronate and lacks activity against 2-sulfoiduronate.
Synonyms: TSULF; DKFZp313G1735; MPS10
Tractability: Antibody: UniProt places it where antibodies can reach, with high confidence; its Gene Ontology location is reachable by antibodies, with high confidence; UniProt predicts a signal peptide or a membrane-spanning region. PROTAC: ubiquitination databases record sites on it; its protein half-life has been measured.
Gene: Protein-coding gene on chromosome 5 (95,555,101 to 95,605,102, forward strand). Ensembl gene ENSG00000164291.
Subcellular location: Secreted; Lysosome
Subcellular location (Human Protein Atlas): Vesicles; Nucleoplasm; Predicted to be secreted
Pathways (Reactome):
Metabolism: Glycosphingolipid catabolism
Metabolism of proteins: The activation of arylsulfatases
Gene Ontology:
Molecular function: arylsulfatase activity; glucuronate-2-sulfatase activity
Cellular component: extracellular region; lysosome; endoplasmic reticulum lumen
Genetic constraint (gnomAD): Loss-of-function variants: 38 observed, 52.23 expected, observed/expected ratio (o/e) 0.73, 90% interval 0.56 to 0.95. The upper end of that interval is the gene's LOEUF score, 0.95, which puts it in group 4 of 6, group 1 being the genes least tolerant of losing a copy. Missense variants: 611 observed, 661.72 expected, observed/expected ratio (o/e) 0.92, 90% interval 0.86 to 0.99. Synonymous variants: 208 observed, 229.28 expected, observed/expected ratio (o/e) 0.91, 90% interval 0.81 to 1.02.
Homologues: Orthologues: chimpanzee ARSK (99% identical), macaque ARSK (96% identical), pig ARSK (90% identical), dog ARSK (89% identical), rabbit ARSK (85% identical), guinea pig ARSK (85% identical), mouse Arsk (82% identical), rat Arsk (82% identical), zebrafish arsk (58% identical), tropical clawed frog arsk (56% identical), Drosophila melanogaster Sulf1 (20% identical), Caenorhabditis elegans sul-1 (18% identical), and 6 more. Paralogues in human: ARSH (21% identical), ARSD (21% identical), STS (21% identical), SULF1 (21% identical), ARSL (21% identical), SULF2 (21% identical), ARSF (20% identical), ARSA (20% identical), GALNS (19% identical), SGSH (19% identical), IDS (19% identical), ARSJ (18% identical), and 4 more.
Diseases named in the same sentence as ARSK in open-access papers:
ARSK is named in the same sentence as 11 diseases in open-access papers, as found by Europe PMC text mining. Sharing a sentence is not in itself a finding about the gene and the disease. The quoted sentences say what the papers report.
mucopolysaccharidosis (2 papers, 2024 to 2025). A group of autosomal recessive or X-linked inherited lysosomal storage disorders affecting the metabolism of mucopolysaccharides, resulting in the accumulation of mucopolysaccharides in the body. "It has been previously reported that ARSK deficiency can lead to a mild form of mucopolysaccharidosis (MPS) in mice due to GAGs accumulation, with no significant lysosomal storage pathology." (PMID 40763656, 2025).
lymphoma (1 paper, 2024). A malignant (clonal) proliferation of B- lymphocytes or T- lymphocytes which involves the lymph nodes, bone marrow and/or extranodal sites. "Immunofluorescence analysis of DLBCL sections showed that every MECR + cell expressed CD20, and the same pattern was observed in RAN + cells or ARSK + cells, indicating the expression of these genes in lymphoma cells." (PMID 38254162, 2024).
ARSK also shares sentences with these, for which no sentence is quoted: breast carcinoma (1 paper); cancer (1); colorectal cancer (1); hepatocellular carcinoma (1); ovarian carcinoma (1); Retinal dystrophies (1); retinopathy (1); trichohepatoenteric syndrome (1); Usher syndrome, type 4 (1).